SEZ6L2 (seizure related 6 homolog like 2)
Description:
May contribute to specialized endoplasmic reticulum functions in neurons.
Synonyms: PSK-1; FLJ90517; BSRPA
Tractability: Antibody: UniProt places it where antibodies can reach, with high confidence; UniProt predicts a signal peptide or a membrane-spanning region; its Gene Ontology location is reachable by antibodies, with medium confidence. PROTAC: ubiquitination databases record sites on it; its protein half-life has been measured.
Gene: Protein-coding gene on chromosome 16 (29,871,159 to 29,899,550, reverse strand). Ensembl gene ENSG00000174938.
Subcellular location: Cell membrane; Endoplasmic reticulum membrane
Gene Ontology:
Biological process: synapse maturation; adult locomotory behavior; cerebellar Purkinje cell layer development
Cellular component: endoplasmic reticulum; neuronal cell body; endoplasmic reticulum membrane; plasma membrane
Genetic constraint (gnomAD): Loss-of-function variants: 44 observed, 96.47 expected, observed/expected ratio (o/e) 0.46, 90% interval 0.36 to 0.59. The upper end of that interval is the gene's LOEUF score, 0.59, which puts it in group 2 of 6, group 1 being the genes least tolerant of losing a copy. Missense variants: 1,086 observed, 1,240.9 expected, observed/expected ratio (o/e) 0.88, 90% interval 0.83 to 0.92. Synonymous variants: 543 observed, 553.96 expected, observed/expected ratio (o/e) 0.98, 90% interval 0.91 to 1.05.
Homologues: Orthologues: chimpanzee SEZ6L2 (99% identical), macaque SEZ6L2 (99% identical), dog SEZ6L2 (97% identical), guinea pig SEZ6L2 (97% identical), rabbit SEZ6L2 (97% identical), rat Sez6l2 (96% identical), mouse Sez6l2 (96% identical), pig SEZ6L2 (94% identical), tropical clawed frog sez6l2 (63% identical), zebrafish sez6l2 (51% identical). Paralogues in human: SEZ6 (44% identical), SEZ6L (43% identical), CSMD2 (22% identical), CSMD1 (21% identical), CSMD3 (21% identical), SVEP1 (19% identical), CR1 (15% identical), CR2 (13% identical), C2 (12% identical), CFB (11% identical), CFH (11% identical), C4BPA (11% identical), and 27 more.
Diseases named in the same sentence as SEZ6L2 in open-access papers:
SEZ6L2 is named in the same sentence as 33 diseases in open-access papers, as found by Europe PMC text mining. Sharing a sentence is not in itself a finding about the gene and the disease. The quoted sentences say what the papers report.
Ataxia (6 papers, 2018 to 2026). Ataxia refers to impaired coordination of voluntary muscle movement. "Antibodies against Seizure-related 6 homolog like 2 (Anti-Sez6l2) have been linked to cerebellar ataxia and retinopathies, associated with various carcinomas including breast and lung." (PMID 41562781, 2026). "SEZ6L2 is a seizure-associated cell surface protein now known to be primarily associated with autoimmune encephalitis and cerebellar ataxia." (PMID 39036049, 2024). "Knock-out mice for the three members of this family exhibit synapse formation abnormalities in the cerebellum, and autoantibodies against Sez6l2 are implicated in an autoimmune syndrome comprising ataxia and retinopathy." (PMID 29958540, 2018). "Autoantibodies against SEZ6L2 have been found in several patients with various forms of ataxia with atypical parkinsonism, which usually occurs due to brain injury in regions controlling muscle coordination, such as the cerebellum." (PMID 37836614, 2023). "Other research has demonstrated that SEZ6L2, a type I transmembrane protein and has Sushi/SCR and CUB domain outside the cellular surface, is highly expressed in the hippocampus and cerebellar cortex, and ataxia occurs in mice lacking members of the SEZ6L2 protein family." (PMID 32148567, 2020).
lung carcinoma (6 papers, 2017 to 2022). "Seizure-related 6 homolog-like 2 (SEZ6L2), which is localized on the cell surface, has been found to be associated with tumor angiogenesis and lung cancer progression." (PMID 32148567, 2020). "SEZ6L2 encoded a seizure‐related protein, which was up‐regulated in lung cancer and was considered to be a novel prognostic marker." (PMID 28796930, 2017). "Their cell-surface study identified SEZ6L2 as a cell-surface marker for lung cancer, which was also identified by our approach as having higher mRNA expression relative to normal tissues." (PMID 29371917, 2017). "Our results suggest that anti-SEZ6L2 antibody treatment may be a promising anticancer therapy that reduces the recurrence of lung cancer in distant organs, such as the brain and bones." (PMID 33202873, 2020). "However, the roles of SEZ6L2 in drug resistance and metastasis in lung cancer remain unclear." (PMID 33202873, 2020). "Previous research on lung cancer showed shorter survival times in patients with tumors exhibiting high SEZ6L2 expression compared with no SEZ6L2 expression, indicating that SEZ6L2 may be a novel prognostic marker for lung cancer." (PMID 33202873, 2020).
autism (5 papers, 2009 to 2024). Persistent deficits in social interaction and communication and interaction as well as a markedly restricted repertoire of activity and interest as well as repetitive patterns of behavior. "For example, two genes within the autism-associated 16p11.2 region, SEZ6L2 and DOC2A, as well as the febrile seizure-associated gene STX1B, were downregulated in carriers of the 16p12.1 deletion." (PMID 34657631, 2021). "SEZ6L2 is an intriguing candidate given the increased risk of clinical or subclinical epilepsy in autism (∼20% of patients)." (PMID 19242545, 2009). "Our most interesting preliminary finding was a recurrent autism-specific R386H amino acid substitution in exon 7 of the seizure-related gene SEZ6L2 that we identified in our initial mutation screen (4/93 autism and 0/93 controls)." (PMID 19242545, 2009). "We found a significant association between autism and a coding variant in the seizure-related gene SEZ6L2 (12/1106 autism vs. 3/1161 controls; p = 0.018)." (PMID 19242545, 2009). "In the present study, we identified an initial significant association between a novel SEZ6L2 coding variant R386H and autism (p = 0.014)." (PMID 19242545, 2009). "To look for additional rare variants in SEZ6L2, we sequenced the remaining 16 exons in an additional 434 autism patients and 185 controls and identified seven autism-specific coding variants (four non-synonymous and three synonymous) and two promoter variants." (PMID 19242545, 2009). "The haploinsufficiency of SEZ6L2 gene might also be associated with language delay, cognitive impairment, and autism." (PMID 39039444, 2024). "The developmental expression pattern of SEZ6L2 in mice and humans is consistent with the neurodevelopmental basis of autism spectrum disorder, thereby providing further support for a role of SEZ6L2 in autism." (PMID 19242545, 2009). "Our expression studies of mouse and human SEZ6L2 in the developing embryo demonstrated high CNS-specific levels of brain expression, as would be expected for a neurodevelopmental disorder such as autism." (PMID 19242545, 2009). "The overall initial pattern of association and specificity to autism as well as the potential role of SEZ6L2 in seizures (which are present in ∼20% of autism cases) warranted further analyses of this gene." (PMID 19242545, 2009). "However, it was suggested that the haploinsufficient dosage of the SEZ6L2 gene may be an important factor in language delay, cognitive impairment, and autism in 16p11.2 microdeletion syndrome." (PMID 36553582, 2022). "Insufficient expression of SEZ6L2 may be an important factor leading to speech delay and autism." (PMID 31391865, 2019).
epilepsy (4 papers, 2011 to 2023). A brain disorder characterized by episodes of abnormally increased neuronal discharge resulting in transient episodes of sensory or motor neurological dysfunction, or psychic dysfunction. "Our analysis showed that the co-expression network associated with SEZ6L2 (2.6 fold, p = 2.2 × 10−9) and PRRT2 (2.52 fold, p = 3.77 × 10−8) were the most highly enriched for proteins in the epilepsy subnetwork, making these priority candidates." (PMID 36808153, 2023). "The SEZ6L2 is an ortholog to a mouse gene that is linked to seizures, and since ASD has high incidence of epilepsy, the human variant is a likely candidate for the cause of this epilepsy." (PMID 22937247, 2011). "SEZ6L2 (Seizure related 6 homolog (mouse)-Like 2) encodes a cell surface protein that has a strong homology with SRPX2 (Sushi-repeat-containing protein, X-linked), mutations in which cause epilepsy and language disorders." (PMID 26872257, 2016).
autism spectrum disorder (3 papers, 2009 to 2020). A spectrum of developmental disorders that includes autism, and Asperger syndrome. "Previous studies have found that a coding variant in SEZ6L2 has a significant association with autism spectrum disorders." (PMID 32148567, 2020). "Seizure-related 6 homolog-like 2 (SEZ6L2), which encodes a seizure-related protein localized on the cell surface, is located in the region of chromosome 16p11.2 and is predicted to be a candidate gene for autism spectrum disorders." (PMID 32148567, 2020).
breast carcinoma (3 papers, 2021 to 2022). "Here, we present the first paraneoplastic case of anti-SEZ6L2 autoimmune cerebellar syndrome caused by breast cancer." (PMID 36310162, 2022). "Serum anti-SEZ6L2 antibodies were markedly increased, and further diagnostic workup revealed left sided breast cancer." (PMID 36310162, 2022). "Specifically, overexpression of SEZ6L2 has been linked to an unfavorable outcome in glioblastoma, colorectal cancer, cholangiocarcinoma, lung adenocarcinoma, non-small cell lung cancer, thyroid cancer, hepatocellular carcinoma, and breast cancer." (PMID 36310162, 2022).
Intellectual disability (3 papers, 2016 to 2021). "Sez6L2 is located in the 16p11.2 deletion/duplication region which encompasses 26 genes and accounts for ~1% of all autism spectrum disorder cases, but also has strong links to schizophrenia and intellectual disability." (PMID 33936031, 2021).
colorectal cancer (2 papers, 2020 to 2022). A primary or metastatic malignant neoplasm that affects the colon or rectum. "Until now, the expression and function of SEZ6L2 in various cancers, including colorectal cancer (CRC), were unclear." (PMID 32105413, 2020). "SEZ6L2 is highly expressed in colorectal cancer and high expression means a poor prognosis." (PMID 35203526, 2022).
glioblastoma (2 papers, 2022). The most malignant astrocytic tumor (WHO grade IV). "High gene expression levels of SEZ6L2 in patients with glioblastoma were found to be a negative prognostic factor." (PMID 36310162, 2022).
lung adenocarcinoma (2 papers, 2020 to 2022). A carcinoma that arises from the lung and is characterized by the presence of malignant glandular epithelial cells. "Seizure-related 6 homolog-like 2 (SEZ6L2) was selected as a gene that was commonly upregulated in both drug-resistant cells and TS cells, and that showed elevated expression in samples from lung adenocarcinoma patients." (PMID 33202873, 2020). "Interestingly, in a mouse model of lung adenocarcinoma, anti-SEZ6L2 antibodies had a positive effect on drug resistance and metastasis." (PMID 36310162, 2022). "Overall, our data showed that SEZ6L2 plays an important role in drug resistance and TS formation and may be a therapeutic target for reducing distant recurrence of lung adenocarcinoma." (PMID 33202873, 2020).
non-small cell lung carcinoma (2 papers, 2018 to 2025). A group of at least three distinct histological types of lung cancer, including non-small cell squamous cell carcinoma, adenocarcinoma, and large cell carcinoma. "Patients diagnosed with non-small cell lung cancer (NSCLC) who have tumors showing elevated SEZ6L2 expression levels tend to experience reduced survival times specific to the tumor, in contrast to individuals without SEZ6L2 expression." (PMID 40230854, 2025). "Another surface protein, SEZ6L2 was identified a novel prognostic marker in non-small cell lung cancer (NSCLC)." (PMID 29560830, 2018).
ovarian carcinoma (2 papers, 2018 to 2021). A malignant neoplasm originating from the surface ovarian epithelium. "No malignancies have been reported with anti-neurochondrin and with anti-SEZ6L2 only 1 patient was identified with a ovarian cancer, diagnosed 4 years later." (PMID 34489848, 2021).
schizophrenia (2 papers, 2021 to 2023). A major psychotic disorder characterized by abnormalities in the perception or expression of reality. "Furthermore, SEZ6L2, CDIPTOSP, ASPHD1, and RANBP1 are potential candidate genes for schizophrenia." (PMID 37486921, 2023).
colon cancer (1 paper, 2025). "Specifically, CDC25C, ANKRD22, SEZ6L2, SERPINA1, and NOS2 were overexpressed in colon cancer tissues compared with normal tissues." (PMID 41425595, 2025).
endometriosis (1 paper, 2025). The growth of functional endometrial tissue in anatomic sites outside the uterine body. "Meanwhile, our study suggested that higher levels of EPHB4, RSPO3, FSHB, and SEZ6L2 were associated with an increased risk of endometriosis, while lower levels of CD109, SAA1, and SAA2 were also associated with an increased risk of endometriosis." (PMID 40450304, 2025). "We found that the druggable genes EPHB4, CD109, SAA1, SAA2, FSHB, and SEZ6L2 may be associated with the pathogenesis of endometriosis and are potential therapeutic targets for drug treatment." (PMID 40450304, 2025). "This study indicates that the druggable genes EPHB4, CD109, SAA1, SAA2, FSHB, and SEZ6L2 may be associated with the pathogenesis of endometriosis and are potential therapeutic targets for drug treatment." (PMID 40450304, 2025). "CD109, SAA1, SAA2, FSHB, and SEZ6L2 are considered to provide low-level evidence of colocalization with endometriosis (PPH4 ≤ 0.6)." (PMID 40450304, 2025). "CD109, SAA1, SAA2, FSHB, and SEZ6L2 are weakly associated with endometriosis, with higher levels of FSHB and SEZ6L2 correlating with an increased risk of endometriosis, and higher levels of CD109, SAA1, and SAA2 correlating with a decreased risk of endometriosis (PFDR < 0.05, PPH4 < 0.6)." (PMID 40450304, 2025).
hepatocellular carcinoma (1 paper, 2020). A malignant tumor that arises from hepatocytes. "However, the role of SEZ6L2 in hepatocellular carcinoma (HCC) is still unclear." (PMID 32148567, 2020).
Insulin resistance (1 paper, 2025). Increased resistance towards insulin, that is, diminished effectiveness of insulin in reducing blood glucose levels. "This revealed that SH2B1-2/SEZ6L2-1 duplications are associated with reduced trunk fat despite higher insulin resistance, a paradoxical finding suggesting leptin pathway modulation." (PMID 40429924, 2025).
mental disorder (1 paper, 2023). A disease that has its basis in the disruption of mental process. "SEZ6L2 (Seizure Related 6 Homolog Like 2), located in 16p11.2, is another gene implicated in mental disorders." (PMID 37486921, 2023).
Obesity (1 paper, 2025). Accumulation of substantial excess body fat. "In our research, 11.86% of the subjects presented with genetic alterations in obesity-associated genes, with 16% of these modifications involving concurrent duplications in SEZ6L2-1 and SH2B1-2, linked to doubled insulin and tripled HOMA-IR levels." (PMID 40429924, 2025).
pancreatitis (1 paper, 2022). Inflammation of the pancreas. "As SEZ6L2 is a marker of pancreatic islet cells, a link to a predisposition to pancreatitis with increased anti-SEZ6L2 antibodies in the body could be speculated." (PMID 36310162, 2022).
cancer (11 papers, 2017 to 2026). A tumor composed of atypical neoplastic, often pleomorphic cells that invade other tissues. "Apart from neurosciences, SEZ6L2-expression has also been linked to different types of cancer, is associated with poor outcome, and therefore can serve as a biomarker and possible therapeutic target." (PMID 36310162, 2022). "The paraneoplastic origin of the cerebellar syndrome observed in our patient is especially interesting in the light of the prognostic value of SEZ6L2 expression in various types of cancer." (PMID 36310162, 2022). "Some of the functions and mechanisms of SEZ6L2 in cancer and other diseases can be inferred through studies of other proteins in the SEZ6 family." (PMID 33202873, 2020). "But further investigation is needed to demonstrated the direct binding targets of SEZ6L2, which may provide solid evidence for understanding the function of SEZ6L2 in cancers." (PMID 32105413, 2020). "Data from the PPI network showed that ASPHD1 is related to several proteins and genes such as KIF22, INO80E, SEZ6L2, and DOC2A, most of which are cancer-related." (PMID 37686578, 2023). "According to previous research, SEZ6L2 has been shown to be regulated by transcription factors, such as STAT3, which upregulate the expression of the vascular endothelial growth factor and promote tumor angiogenesis and cancer progression." (PMID 32148567, 2020). "For example, SEZ6L2 was higher ranked than CA9 in our analysis but CA9 was selected due to the availability of molecular imaging probes targeting this marker and based on its potential applicability among several cancer types." (PMID 29371917, 2017).